FASN (fatty acid synthase)
Diseases named in the same sentence as FASN in open-access papers (continued):
Sharing a sentence is not in itself a finding about the gene and the disease.
breast cancer (continued). "However, only ectopic miR-15a-16-1, but not miR-497-195, markedly reduced the levels of endogenous FASN in breast cancer cells." (PMID 27713175, 2016). "Our findings provide evidence that microRNA-195 attenuates epithelial-mesenchymal transition (EMT) in breast cancer cells by targeting FASN, HMGCR, ACACA and CYP27B1 and strongly suggest that overexpression of miR-195 may have therapeutic value in treating breast cancer." (PMID 26632252, 2015). "Thus, breast cancer cells that overexpress HER2 and have increased FASN activity may sustain their proliferation and avoid lipotoxicity by converting and storing excess palmitate as triglycerides." (PMID 26640797, 2015). "We hypothesized that FASN was the key downstream effector of the bidirectional ER/HER2 crosstalk that promotes malignant phenotypes, such as proliferation, migration, apoptosis evasion and endocrine resistance, in ER+/HER2+ breast cancer cells." (PMID 24866893, 2014). "FASN is highly expressed in breast cancer but not in nonlactating normal breast tissue." (PMID 24778702, 2014). "In contrast to fatty acid synthesis being downregulated in most normal human tissues, precancerous lesion and cancer cells upregulate fatty acid synthesis resulting in the high expression of FASN independent of dietary fat and independent of hormonal regulation in breast cancer." (PMID 24778702, 2014). "FASN catalyzes the synthesis of palmitate from malonyl CoA and acetyl CoA via NADPH and is minimally expressed in most normal human tissues, with the exception of cycling endometrium, the lactating breast, and aggressive subsets of human carcinomas, including certain breast cancers." (PMID 21294903, 2011). "Therefore, the AMPK-induced threonine phosphorylation of FASN likely did not play a role in the regulation of FASN activity by the relatively low dose of lapatinib or C75 we used in HER2-positive breast cancer cells." (PMID 21080941, 2010). "Additionally, the stability of FASN at the protein level in breast cancer tissues is regulated by small ubiquitin‐like modifier (SUMO)‐mediated SUMOization of ubiquitin‐like protein modifier molecules, which stabilize FASN from degradation in the protease environment and promote FASN expression." (PMID 39584783, 2024). "Taken together, these results suggest that FASN may function as a tumor-cell-intrinsic marker of immune resistance that can be targeted to (re)sensitize highly aggressive cancer subtypes (e.g., HER2 + /PD-L1-overexpressing basal/HER2 breast cancer) to T-cell immunity." (PMID 39349429, 2024). "In this context, several studies conducted in HER2+ breast cancer (BC) revealed the existence of a reciprocal positive feedback loop between HER2 and the lipogenic enzyme FASN, whose upregulation can represent an important mechanism of resistance to anti-HER2 agents." (PMID 36753044, 2023). "Furthermore, in HER2-overexpressing breast cancer cells, piperineis strongly inhibits proliferation, induces apoptosis, and enhances paclitaxel sensitization through inhibition of SREBP-1/FASN signaling, which might be mediated by HER2 expression, ERK1/2, p38, and Akt signaling pathways." (PMID 35912181, 2022). "In addition, miR‐195 can directly target acetyl‐CoA carboxylase alpha (ACACA), FASN, HMGCR, and CYP family 27 subfamily B member 1 (CYP27B1) resulting in modulation of de novo GA/cholesterol synthesis and the inhibition of proliferation and invasion of breast cancer cells." (PMID 34766135, 2021). "Interestingly, piperine suppressed the expression of fatty acid synthase through the inhibition of extracellular signal-regulated kinase 1/2 (ERK1/2) and the reduction of mature sterol regulatory element-binding protein-1 (SREBP-1), leading to apoptosis in HER2-overespressing breast cancer cells." (PMID 33256185, 2020).
breast cancer (continued). "Besides, fatty acid synthase (FASN), a key enzyme in the fatty acid synthesis pathway, was reported to be involved in multiple drug resistance, such as docetaxel/trastuzumab resistance in breast cancer and gemcitabine or radiation resistance in pancreatic cancer." (PMID 29489864, 2018). "Indeed the aggressive “triple-negative” breast cancer cell lines express lipoprotein lipase (LPL), the key enzyme for extracellular lipolysis, and the transmembrane channel for exogenous free FA uptake (CD36), together with the classical lipogenic markers such as FASN." (PMID 26452259, 2015). "Consistent with the proposal that fatty acid scavenging would reduce dependence on FASN, supplementation with necrotic cell debris rescued macropinocytic MCF-7, but not non-macropinocytic HCC1569, breast cancer cells from GSK2194069." (PMID 32111826, 2020). "Since levels of FASN in DU-145 and MDA-MB-231 were lower than in the other prostate or breast cancer cell lines, these were not detectable on the same gel." (PMID 28066718, 2016). "We further confirmed dephosphorylation of FASN by lapatinib by measuring total and phosphorylated FASN levels in HER2-positive SKBR3 and BT474 breast cancer cells with or without treatment with a clinically relevant concentration of lapatinib overnight." (PMID 21080941, 2010). "In breast cancer BT-474 cells that overexpress HER2, the expression of FASN and ACC are not mediated by SREBP-1, but by a mammalian target of rapamycin (mTOR)-dependent selective translational induction." (PMID 19352381, 2009). "However, a higher expression level of FASN was found to be link to poor OS, RFS, distant-metastasis free survival (DMFS) only in breast cancer patients with HER2 negative." (PMID 37124526, 2023). "In this study, FASN expression was not correlated with prognostic markers, such as OS or DFS, or pathological features, such as nodal metastasis, TNM stage, histological grade, ER status, PR status, and Ki-67 index, of breast cancer patients." (PMID 37124526, 2023). "However, high FASN expression was related to poor OS, RFS, DMFS, and PPS in breast cancer cases with HER2 negative subtype/mesenchymal." (PMID 34879004, 2021). "We hypothesized that proliferation of MCF-7 cells, an estrogen-dependent human breast cancer cell, might be inhibited by DHA by reducing levels of p-SREBP-1, m-SREBP-1, and FASN and inhibiting downstream signaling, while AA would have no such effect." (PMID 29282029, 2017). "Indeed, CCN1 overexpression was sufficient to increase steady-state FASN protein to levels similar to those found in SKBR3 cells (data not shown), a naturally occurring FASNoverexpressing breast cancer cell line." (PMID 27713913, 2016). "However, studies with siRNAs revealed that, as with FASN inhibition, ACC inhibition triggers apoptosis in prostate and breast cancer cells, but not in nonmalignant cells." (PMID 19352381, 2009). "To investigate whether FASN signaling is involved in maintaining constitutive PD-L1 overexpression, we took advantage of JIMT-1 cells, a unique model of breast cancer with 100% of the cells being PD-L1 positive without involving an increased PD-L1 gene copy number." (PMID 39349429, 2024). "In addition, 25HC has been demonstrated to promote the differentiation of Leydig cells, hepatocytes and keratinocytes and to induce fatty acid synthase (FAS) expression, as we confirmed to occur also in a cell context lacking ERs like SkBr3 breast cancer cells." (PMID 21304949, 2011).
Obesity (203 papers, 2009 to 2026). Accumulation of substantial excess body fat. "Our work elucidates the adipocyte-specific DDRGK1-UFMylation-FASN axis as a novel therapeutic target for obesity-associated metabolic dysfunction." (PMID 41671397, 2026). "For instance, miR-33 is directly involved in hepatic lipogenesis in chickens, as it regulates fatty acid synthase (FASN) and represses the fat mass and obesity-associated gene, influencing lipid metabolism and storage during development." (PMID 41301939, 2025). "Molecular heterogeneity is a major characteristic of tumors, and obesity is associated with more indolent molecular variants, including reduced fatty acid synthase (FASN) expression." (PMID 38741777, 2024). "In humans, genetic variation within FASN is associated with obesity, and high transcriptional activation of FASN occurs in cancer cells." (PMID 37695169, 2023). "With the use of HKO mice with diet-induced or genetic obesity, we now show that hepatic FASN deficiency differentially affects NAFLD and diabetes in a manner dependent on the etiology of obesity." (PMID 37681411, 2023). "For example, FASN is a gene encoding for a fatty acid synthase and is known to play a key role in the regulation of obesity; an increased FASN expression was associated with an impaired insulin sensitivity." (PMID 32709145, 2020). "In the context of insulin resistance and T2D, deficiency of the SREBP target gene fatty acid synthase (FASN) in macrophages leads to a hyperinflammatory and metabolically perturbed phenotype upon diet-induced obesity." (PMID 32785109, 2020). "Previous studies have demonstrated that FASN is associated with various human diseases, including obesity, inflammation, cardiovascular disease and cancer, in particular." (PMID 32699531, 2020). "FASN overexpression has been associated with a poor prognosis in breast and prostate cancer patients and is an attractive potential target for obesity and cancer therapies." (PMID 26621841, 2016). "Just like PPARγ, fatty acid synthesis enzymes such as FASN have been implicated in almost all aspects of human metabolic alterations such as obesity, insulin resistance or dyslipemia." (PMID 20148112, 2010). "To clarify the effects of hepatic FASN deficiency on NAFLD and diabetes in obese mice in the setting of NCD overfeeding without leptin deficiency, we next studied Mc4r-KO mice as an alternative mouse model of hyperphagic obesity associated with hepatic FASN upregulation and hyperleptinemia." (PMID 37681411, 2023). "Many substances associated with obesity such as fatty acid synthase, fatty acid binding protein, phospholipase A2, and adipokines may be involved in the development of head and neck cancer." (PMID 37620971, 2023). "However, the mechanisms of such suppression appear to differ between the 2 mouse models of genetic obesity, with hepatic FASN deficiency attenuating PPARα activity and activating AMPK in ob/ob mice but not in Mc4r-KO mice." (PMID 37681411, 2023). "Inhibition of hepatic FASN may therefore be a potential therapeutic strategy for obesity-associated NAFLD and T2D in humans." (PMID 37681411, 2023). "Lower FASN protein levels, a central lipogenesis enzyme that catalyses de novo saturated FA biosynthesis, has been associated with hyperglycaemia, insulin resistance and obesity." (PMID 38146533, 2023). "Interestingly, FASN expression is directly linked to obesity and type 2 diabetes and CD36 protein expression is upregulated in both obese patients and type 2 diabetics." (PMID 32850342, 2020). "Scd1, for example, catalyzes the rate-limiting reaction of monounsaturated fatty acid synthesis and is regulated by leptin, a key regulator of obesity-linked diabetes, through insulin independent mechanisms while FASN deregulation is linked to metabolic diseases and insulin-resistance." (PMID 27855634, 2016). "The reason that obesity carries may have higher risk of colon cancer is because of increased activity of fatty acid synthase (FASN) in the tumor." (PMID 23202913, 2012).
Obesity (continued). "The correlation between FASN expression and the different parameters that are associated with diabetes and obesity have shown the following results: there is a positive correlation of FASN expression with levels of adiponectin (P < 0.05; r = 0.265) and HDL-c (P < 0.05; r = 0.276)." (PMID 20148112, 2010). "We contribute to study the role of FASN with a general population with a wide range of body mass index (BMI) and metabolic parameters, in order to clarify the association between FASN activity/expression, the grade of insulin resistance and obesity-related insulin resistance." (PMID 20148112, 2010). "However, the therapeutic potential of targeting FASN in hepatocytes for obesity-associated metabolic diseases is unknown." (PMID 37681411, 2023). "IL6, IL8, IL1B, CXCR4, and FASN showed significantly higher levels, and since FASN polymorphisms have been associated with elevated BMIs, they suggested FASN maybe a genetic biomarker link between obesity and poor PCa outcome." (PMID 33599076, 2021). "In contrast to its expression in most normal tissues, FASN is overexpressed in several cancers (43, –, 47), diabetes, obesity, and non-alcoholic fatty liver disease (NAFLD)." (PMID 40558086, 2025). "Orlistat is an FDA-approved anti-obesity drug that targets the FASN thioesterase activity, although it also irreversibly inhibits pancreatic and gastric lipases." (PMID 40558086, 2025). "Orlistat is a well-known irreversible inhibitor of pancreatic and gastric lipase, as well as a fatty acid synthase inhibitor, and it is commonly used to treat obesity and prevent atherosclerosis." (PMID 41002434, 2025). "Currently, the FDA has approved drugs targeting FASN for obesity treatment, which also display potential role in blocking lipid synthesis in tumors; however, the clinical application of these drugs is limited by the development of drug resistance." (PMID 40814339, 2025). "Beyond AD, the therapeutic relevance of FASN inhibition extends to various diseases, including cancer, fatty liver disease, obesity, and type 2 diabetes, underscoring its broad therapeutic potential." (PMID 40327680, 2025). "This figure shows that obesity promotes the excessive synthesis of saturated and unsaturated fatty acids by upregulating the expression of fatty acid synthase (FASN)." (PMID 40414892, 2025). "This miRNA alleviates obesity-initiated MASLD by repressing the expression of fatty acid synthase and stearoyl-CoA desaturase." (PMID 39424772, 2025). "Conversely, reduced hepatic lipid synthesis was observed by decreasing sterol regulatory element-binding protein 1c (SREBP-1c) and fatty acid synthase (FASN), suggesting an anti-obesity and cardioprotective effect." (PMID 41550864, 2025). "Orlistat is a Food and Drug Administration (FDA)-approved anti-obesity drug that inhibits fatty acid synthase (FASN)." (PMID 39069526, 2024). "Diet-induced obesity exacerbates melanoma progression in male C57BL/6J mice, which is associated with the elevated expression of Caveolin-1 (Cav-1) and FASN in tumors from mice on a high-fat diet." (PMID 38921444, 2024). "The authors have demonstrated that the liver expression of SREBP1 and its downstream target genes (ACC, ACL, and FASN) is suppressed by the supplementation of soy isoflavones in diet-induced obesity rats." (PMID 38791455, 2024). "Soya beans are also able to mitigate obesity-induced metabolic disorders as they lower triglyceride levels and have fatty acid synthase inhibitory activity, which contribute to ameliorating diabetes-related complications." (PMID 39519546, 2024). "Orlistat is used to treat obesity by inhibiting fatty acid synthase, but it has been recently investigated for the treatment of cancer, as fatty acid synthase is often overexpressed in cancer." (PMID 39459317, 2024).
Obesity (continued). "Research indicates that theaflavins TF1, TF2a, and TF3 enhance glucose and lipid metabolism in mice on a HFD by activating the SIRT6/AMPK/SREBP-1/FASN pathway, thus effectively mitigating obesity symptoms." (PMID 39606571, 2024). "Orlistat, beyond known for its traditional role in obesity management by inhibiting lipase, has shown promise as a cancer treatment agent due to its effect on FASN." (PMID 39524139, 2024). "Nevertheless, FASN gene expression has been broadly related to the regulation of body weight and the development of obesity." (PMID 38256201, 2024). "Orlistat, an FDA-approved drug used for obesity, effectively inhibits pancreatic and gastric lipases by targeting the thioesterase domain of FASN, thus exerting its therapeutic effects." (PMID 38921444, 2024). "The fatty acid synthase (FASN) inhibitor tetrahydrolipstatin (orlistat), used to treat obesity, represents a potential new option for antitumor therapy." (PMID 38672673, 2024). "Significant increases were observed in Ccnd1, a cell cycle regulator that contributes to tumorigenesis, and Fasn, a fatty acid synthase that promotes obesity and tumorigenesis, in PFAS-exposed mice." (PMID 38251008, 2024). "Concerning lipogenesis, AME supplementation decreased the mRNA level of FASN, which synthesizes fatty acid from acetyl-CoA and malonyl-CoA de novo and is recognized as a potential functional food targeting obesity-related health risks." (PMID 37223261, 2023). "We have shown that hepatic FASN deficiency differentially affects NAFLD and diabetes in a manner dependent on the genetic and dietary background of obesity." (PMID 37681411, 2023). "In this study, we focused on investigating the mechanism by which FASN modulated lung endothelial homeostasis under obesity in LPS-induced ALI." (PMID 36922854, 2023). "To maximize the effect of hepatic FASN deficiency, we therefore next studied ob/ob mice fed an NCD, which develop hyperphagic obesity associated with hyperinsulinemia." (PMID 37681411, 2023). "At the onset of obesity, high lipid amounts accumulate in the white adipocytes related to fatty acid synthase, sterol regulatory binding protein 1c (SREBP1c), and acetyl-CoA carboxylase activity." (PMID 36457182, 2023). "To study the in vivo effect of FASN inhibition on endothelial barrier function in obesity, we next determined alterations in vascular permeability by EBD assay, lung wet-to-dry (W/D) ratio, and BALF protein concentration." (PMID 36922854, 2023). "MCL cell lines, in which FASN is highly and consistently expressed, exhibited significant apoptosis when treated with orlistat, an anti-obesity drug, which is also an inhibitor of FASN and is approved by the FDA." (PMID 36982568, 2023). "Here, we show that hepatic FASN deficiency differentially affects NAFLD and diabetes depending on the etiology of obesity." (PMID 37681411, 2023). "In this present study, we set out to identify the role of endothelial FASN in LPS-induced ALI in mice with obesity." (PMID 36922854, 2023). "Bee bread polyphenols significantly reduced the obesity index by inhibiting fatty acid synthase activity in the high-fat diet-induced obese rats." (PMID 36829976, 2023). "This study aimed to investigate the role of fatty acid synthase (FASN) in lipopolysaccharide (LPS)-induced ALI under obesity." (PMID 36922854, 2023). "The therapeutic potential of targeting hepatic FASN in obesity-related metabolic diseases has thus remained unclear." (PMID 37681411, 2023). "Collectively, our findings revealed that upregulated FASN was involved in disrupting lung endothelial homeostasis, which probably led to enhanced susceptibility to LPS-induced ALI in obesity." (PMID 36922854, 2023). "FASN inhibition in obesity attenuated the exacerbation of lung inflammatory injury in response to LPS via rescuing lung endothelial dysfunction." (PMID 36922854, 2023).